CX3CR1 (C-X3-C motif chemokine receptor 1)
Diseases named in the same sentence as CX3CR1 in open-access papers (continued):
Sharing a sentence is not in itself a finding about the gene and the disease.
tumor (continued). "Few studies also indicated the possible role of CX3CR1-mediated angiogenic switch regulating malignant transition where macrophage may play a pivotal role in vascular remodelling in different tumor models." (PMID 37770496, 2023). "After three weeks, CX3CR1-depleted mice displayed reduced tumor progression." (PMID 38001732, 2023). "Thus, the increase of CX3CR1+CD8+ T cells within the spleen during T cell priming in the presence of ICI therapy may correlate with an increased migratory capacity of effector CD8+ T cells eventually facilitating their enrichment at tumor sites to cause tumor regression." (PMID 36656137, 2023). "Evidence also showed that CX3CR1 was expressed at a lower level in M1 macrophages but at a higher level in M2 macrophages, which can extensively be involved in the migration and survival of tumor cells, confirming the accuracy of subtyping results." (PMID 38143770, 2023). "The first highest order miR-200 family-associated subnetwork motif comprised miR-200a-3p, CX3CR1 and SPIB. miR-200 family has been reported to function as an oncogene or tumor-suppressor in several carcinogenesis, but its crucial biological importance and functions in NSCLC are subtle." (PMID 37770496, 2023). "From these results, we hypothesized that antibody-targeting of CX3CR1 could reduce the abundance of immune suppressive myeloid populations in the tumor." (PMID 37771579, 2023). "A study revealed that in monocytic MDSCs, upregulation of senescence regulatory molecules p16 and p21 inhibits CDKs-mediated phosphorylation and inactivation of SMAD3, resulting in high expression of the chemokine receptor CX3CR1, culminating in enhanced tumor growth via the CX3CL1/CX3CR1 axis." (PMID 37046588, 2023). "Since CX3CL1 signaling through CX3CR1 leads to secretion of immunosuppressive mediators by the CT26 tumor, we hypothesized that CX3CR1 antibody could reduce the secretion of these mediators." (PMID 37771579, 2023). "This study shows the utility of T-cell differentiation marker, CX3CR1, as an early on-treatment predictor of response and changes in genomic/transcriptomic signatures of circulating tumor-infiltrating lymphocyte repertoires in patients with NSCLC undergoing chemo-immunotherapy." (PMID 37009132, 2023). "In the tumor, CX3CR1 expression was higher in CD45+CD11b+ than CD45+CD11b- cells." (PMID 37771579, 2023). "In addition, the CX3CR1 mAb reduces secretion of soluble mediators from the tumor and reduces the abundance of immune suppressive myeloid cell populations while increasing the percentage of mature macrophages." (PMID 37771579, 2023). "We treated the CT26 tumor model with anti CX3CR1 alone and in combination with anti-PD-1." (PMID 37771579, 2023). "Furthermore, Th17 cells can produce IL‐21, which contributes to the generation and infiltration of CX3CR1+CD8+ T cells to promote tumor clearance in the melanoma model." (PMID 37829505, 2023). "The CX3CR1-positive tumor cells could adhere to nearby infiltrating ganglia and neural cells expressing CX3CL1, which were preferred to local rather than distant tumor in human PDAC." (PMID 35478937, 2022). "CX3CR1 was lower in Asian patient tumor samples based on RNA gene counts." (PMID 35754051, 2022). "In our study, we demonstrated the role of CX3L1 in recruiting tumor cells expressing CX3CR1." (PMID 35478937, 2022). "In a hepatocellular carcinoma murine model, the hypoxic environment in the tumor caused hypoxia-inducible factor-1 (HIF-1) to activate CXCL26 transcription in cancer cells, thereby recruiting MDSCs expressing the CXCL26 receptor CX3CR1 into the primary tumor site." (PMID 35854339, 2022). "Moreover, to verify the recruitment of CX3CL1 to the CX3CR1-expressing tumor cells in PDAC liver metastasis of PDAC, we performed the transwell experiments by using in vitro recombinant protein." (PMID 35478937, 2022).
tumor (continued). "In addition, NK cells express certain receptors on their surface, such as the chemotactic receptor CX3CR1, which can drive the accumulation of these cells toward peripheral tissues, including tumor sites." (PMID 36189271, 2022). "Soluble CX3CL1 might also bind to CX3CR1 expressing tumor cells and trigger tumor cell proliferation." (PMID 34070094, 2021). "Moreover, the frequency of Tet+ CD8+ T cells remained higher in the CX3CR1+ subset than in the CX3CR1− subsets in both tumor models, suggesting that the PB CX3CR1+ subset is enriched with tumor-specific CD8+ T cells." (PMID 33658501, 2021). "In addition, we observed that lower expression of CX3CR1 was correlated with tumor T and N stages, differentiation, and poorer prognosis." (PMID 35140706, 2021). "Thus, redirecting progenitor cell differentiation towards CX3CR1+ effector cells will likely help overcome functional exhaustion of tumor-reactive CD8+ T cells." (PMID 33809259, 2021). "CX3CR1 was not significantly related to age, gender, tumor location, size, and M stage but was associated with T and N stages, tumor differentiation, and prognosis of the tumor." (PMID 35140706, 2021). "Indeed, these studies suggest that the major monocyte recruiting pathways (M-CSF/CSF-1R, CCL2/CCR2, CCL3/CCR1, CCL3/CCR5, CCL5/CCR5 and CX3CL1/CX3CR1) enable tumor survival by supplying the TME with pro-tumorigenic TAMs." (PMID 34988021, 2021). "Trajectory analyses reveal exhausted CD8+ T and immune-suppressive TNFRSF4+ Treg cells in tumours might derive from peripheral CX3CR1+CD8+ T and naïve Treg cells, respectively." (PMID 33531485, 2021). "In addition, it was showed that chemokine CX3CL1 interacts with its receptor CX3CR1 to induce TAM recruitment into tumor tissues and promote skin cancer progression." (PMID 34178692, 2021). "However, if a drug called a CX3CR1 antagonist is used to antagonise the receptor for fractalkine, we can restore NK cell movement towards the tumour." (PMID 35008227, 2021). "In addition, our data provide novel insights into the utility of combining CX3CR1 antagonism with IL-15 to boost NK cell tumour-homing and tumour-killing in OAC patients." (PMID 35008227, 2021). "CX3CL-1 is said to bind CX3CR1+ tumour cells, aimed at organs, trigger movement of cancer cells." (PMID 34336101, 2021). "Notably, mice harboring LFA-1-overexpressing NSCLC cells developed more severe spine-metastatic lesions radiographically and higher tumor burdens histologically compared with CX3CR1-KD mice, which was comparable to those in control groups." (PMID 33754027, 2021). "While CM promotes tumorigenesis and metastasis, NCM are actively recruited to the lungs in a CX3CR1-dependent way and interact with metastasizing tumor cells, gather tumor cell debris from the lung vasculature and recruit and activate natural killer cells (NKs)." (PMID 32824655, 2020). "If tumor cells express mCX3CL1 and CX3CR1 simultaneously, these cells will stick together." (PMID 32466280, 2020). "CX3CL1 was the ligand of chemokine CX3CR1, which could promote tumor infiltrating cells into tumor microenvironment and play the role of immunotherapy." (PMID 32780567, 2020). "Seven days after tumor cell inoculation, the CX3CR1+ cell motility changed significantly." (PMID 33133103, 2020). "Interestingly, some populations of infiltrating immune cells in the tumor also showed high levels of CX3CR1 expression." (PMID 32764562, 2020). "Additionally, 35% of TAM‐BMDM expressed YFP (Fig EV2A–C), in accordance with the known expression pattern of the Cx3cr1 promoter in these tumours." (PMID 32567735, 2020). "Increased expression of CX3CL1 and CX3CR1 in a tumor is both anti-cancer and pro-cancer." (PMID 32466280, 2020). "Therefore, a study in PDAC patients showed evidence that high expression of the CX3CL1/CX3CR1 axis in tumor tissues led to a poor prognosis for OS." (PMID 31991604, 2020). "This process is significant in a GBM tumor, characterized by high expressions of CX3CR1 and CX3CL1." (PMID 32466280, 2020).
tumor (continued). "Furthermore, in HCC patients, CX3CL1/CX3CR1 regulates the cancer cell cycle and tumor progression via the autocrine or paracrine systems, which is associated with positive outcomes." (PMID 31991604, 2020). "Interestingly, these pathways are utilized by a series of chemokines and their receptors, such as CCL20/CCR6, CCL25/CCR9, CXCL1/CXCR2, CXCL8/CXCR1-2, CXCL12/CXCR4, and CX3CL1/CX3CR1, to inhibit apoptosis and promote tumor cell growth and proliferation." (PMID 31991604, 2020). "An increase in CX3CR1 expression alone may indicate an increase in the number of the cells of the immune system in a tumor and an active anti-tumor response." (PMID 32466280, 2020). "While cleavage and its functional consequences of CXCR3 and CX3CR1 chemokines by proteases have been rather well characterized on the biochemical level, there is hardly any in vivo data on the impact of these cleavage processes on tumor-immune interactions." (PMID 31482487, 2019). "Indeed, the CX3CL1/CX3CR1 axis is involved in the interaction between tumor cells and the microenvironment by the regulation of tumor cell invasion, migration, and adhesion and promotes bone metastasis." (PMID 30845779, 2019). "The microarray data revealed 728 distinctly regulated genes between two populations and the top highly expressed genes (IL2RB, GZMA, GZMB, EMR4, PRF1, CX3CR1, STAT1, and TLR9) in lung-derived Ly6C+ cells from EMT6 tumor-bearing mice are associated with effector T-cell function." (PMID 30926774, 2019). "This direct effect on tumor cells may relate to the fact that the tumor cells themselves express CX3CR1, whose activation directly triggers proliferation and migration." (PMID 31482487, 2019). "We cannot investigate all the CX3CR1 expressing immune cells in the tumor." (PMID 31367257, 2019). "Moreover, expression of the transmembrane form of CX3CL1 in neurons, endothelial cells or peritoneal cells promotes tumor cell adhesion and site-specific metastasis of CX3CR1-expression prostate, ovarian, or pancreatic tumor cells." (PMID 31482487, 2019). "The pathophysiological role of the CX3CL1/CX3CR1 axis in the interaction between tumor cells and the microenvironment has been demonstrated in several solid tumors, such as breast and prostate and in different types of B cell lymphomas and chronic lymphocytic leukemia." (PMID 30845779, 2019). "Importantly, our data indicate that even transient downregulation of CX3CR1 in combination with other tested therapies brings about measurable DNA damage resulting in long-term deleterious effects on tumor growth." (PMID 29712888, 2018). "Moreover, our studies suggest that downregulation of CX3CR1 allows using significantly lower doses of x-ray to achieve the same effects, which may carry a promise of reducing radiation dose and associated toxicities while maintaining the same efficacy in killing tumor cells." (PMID 29712888, 2018). "CX3CR1 is considered a marker for resident intestinal macrophages, which play a central role in regulating inflammation, and its absence has been correlated with dysregulated inflammatory response, tissue damage and higher tumor occurrence." (PMID 30140377, 2018). "Future studies are warranted to define whether the efficacy of CIT is dependent on certain ICI to recruit immune cells into tumor tissues (like CX3CR1+CD8 effector T cells) or to expand local tumor-infiltrating immune cells to reject tumors." (PMID 30100909, 2018). "The blockade of CX3CR1 improved HPMo recruitment to SKBR7 tumours." (PMID 29367702, 2018). "Our studies indicate that expression of CX3CR1 correlates with that of several proteins responsible for FA uptake, and, thus, might contribute to reduced tumor growth." (PMID 29712888, 2018). "However, irradiation alone did significantly reduce spleen tumor burden, while a combination of irradiation and downregulation of CX3CR1 resulted in significantly greater reduction of tumor burden compared to radiation alone." (PMID 29712888, 2018).
tumor (continued). "CX3CR1 was involved in four signatures that were grouped to different tumour subtypes." (PMID 29699511, 2018). "Notably, blockade of the CX3CL1/CX3CR1 axis suppresses tumour growth, whereas inactivation of CDKs elicits the opposite effect." (PMID 29234059, 2017). "Although the pro-angiogenic effect of CD11b+CX3CR1+ monocytes has not been well described in human cancer types, these findings suggest that CD11b+CX3CR1+ monocytes might promote tumor growth and progression by enhancing angiogenesis in DLBCL." (PMID 29190915, 2017). "Therefore, although previous studies have suggested the immunosuppressive role of CD11b+CX3CR1+ monocytes in the tumor microenvironment, the mechanism of these cells in DLBCL needs to be further clarified." (PMID 29190915, 2017). "In addition to their pro-angiogenic capacity, PB-CD11b+CX3CR1+ monocytes can suppress host anti-tumor immune responses." (PMID 29190915, 2017). "Tumor tissues set up different strategies to escape immune recognition and in particular to affect chemokine/chemokine receptor axes such as CX3CL1/CX3CR1, which are crucial for the recruitment of cells such as CD56dim NK cells exerting tumor suppressive properties." (PMID 28791023, 2017). "CX3CR1 is frequently used to identify microglia in tumor specimen." (PMID 29262845, 2017). "The correlation between the fractalkine/CX3CR1 axis and tumor progression remains controversial." (PMID 28903329, 2017). "In this study, we investigated whether the in vivo tumor trafficking of activated T cells could be enhanced by the expression of the chemokine receptor CX3CR1." (PMID 27096098, 2016). "Overall, these results demonstrate that T cells expressing the chemokine receptor CX3CR1 show increased homing towards tumors producing the specific ligand, and highlight the critical issue of a gradient between peripheral tissues and the tumor." (PMID 27096098, 2016). "Because CX3CR1 is expressed in a wide variety of cell types, it is controversial whether the CX3CL1–CX3CR1 axis is tumor-suppressive or tumor-promotive." (PMID 27136535, 2016). "This method allowed us to investigate the role of microglial CX3CR1 on tumor growth." (PMID 25987130, 2015). "Loss of Cx3cr1 in microglia in a monocyte-free environment had no impact on tumor growth and did not alter microglial migration." (PMID 25987130, 2015). "In conclusion, the CX3CR1/CX3CL1 axis could represent a potential therapeutic approach using antagonists to CX3CR1 capable to inhibit tumor neurotropism in PADC." (PMID 24799766, 2014). "Because there are fewer chemokine receptors than chemokine ligands, we first assessed the levels of expression of mRNAs encoding all 18 types of chemokine receptors (CXCR1-6, CCR1-10, XCR1, and CX3CR1) in the inflammatory cells located around the tumor in our patient." (PMID 25123545, 2014). "Furthermore, we found that development of metastatic liver tumors was substantially inhibited in CX3CR1−/− mice as compared with WT littermates, suggesting the critical role of CX3CR1 expression in TAMs-mediated tumor development." (PMID 24245985, 2013). "In this study, we explored whether CX3CR1, a chemoattractant cytokines receptor, regulates the TAMs subtypes in the tumor microenvironment, for several reasons." (PMID 24245985, 2013). "Although CX3CR1 plays a positive role in neovascularization, the mechanism by which CX3CR1 regulating macrophage function contributing to tumor development remains unclear." (PMID 24245985, 2013). "However, the role of CX3CR1 in the regulation of the tumor inflammatory microenvironment is not fully understood." (PMID 24245985, 2013). "In line with this hypothesis, we showed that the constitutive production of CX3CL1 by malignant epithelial ovarian cells led to the release of the soluble form of this chemokine, which binds to CX3CR1 present on tumor cells." (PMID 21750716, 2011).
tumor (continued). "Furthermore, normal epithelial cells express higher levels ofCX3CL1 respect to their tumour counterpart while itsreceptor (CX3CR1) is expressed in tumour cells." (PMID 21479216, 2011). "As a result of both the adhesion and chemoattractant activities of the chemokine, the CX3CL1/CX3CR1 complex may mediate either pro- or anti-tumor effects." (PMID 21750716, 2011). "Additionally, within the tumor microenvironment, two distinct tumor-associated macrophage (TAM) clusters were enriched in PitNETs, one with pro-inflammatory M1 features and the other with immunosuppressive M2 marker upregulation (SPP1, TREM2, and CX3CR1)." (PMID 40959438, 2025). "Consequently, these results propose that CX3CR1+ macrophages may trigger apoptosis in tumor cells through the INHBA-ACVR1B axis." (PMID 38658971, 2024). "However, CX3CR1 expressed significantly increasing in most tumor tissues." (PMID 38241595, 2024). "The authors suggested that profiling T cells expressing CX3CR1 in peripheral blood not only identifies patients with improved clinical benefit, but also serves as a dynamic marker to identify T cell repertoires that are reflective of tumor-infiltrating lymphocytes." (PMID 38493133, 2024). "CXCR3 expression remained markedly lower in the CX3CR1+ subset than in the CX3CR1− subset of Pmel-1 T cells in the spleen, suggesting that peripheral CX3CR1+ Pmel-1 T cells have a decreased capacity to migrate to the tumor microenvironment via the CXCR3-CXCL9/CXCL10 axis." (PMID 38881188, 2024). "Hence, the release of CX3CL1 by the MTX-induced dying cancer cells may establish a gradient directed towards the tumour, presumably augmenting CX3CR1+ immune cell migration along the gradient and activation of an anti-tumour immune cycle." (PMID 39011040, 2024). "We speculated that CX3CR1+ cells that have already circulated in patients affect hematogenous and lymphatic metastasis and they then migrate in the abdominal cavity by surgical procedure getting tumor cells to escape antitumor immunity to disseminate." (PMID 38433196, 2024). "However, due to the elevated concentration of CX3CL1, cancer cells expressing CX3CR1 might also be retained within the tumour and become the target of immune cells." (PMID 39011040, 2024). "In our vaccine setting, we hypothesize that favors the induction of T cell-derived IFN-γ and other signals that drives monocyte polarization to iNOS+ macrophages upon entering the tumor, but other signals promote maintenance, expansion, or induction of CX3CR1+CD206+ macrophages as well." (PMID 38187708, 2024). "As our knowledge deepens of the important cell types involved in the anti-tumor response mediated by anti-CX3CR1 mAb, an adaptation of the mAb design into a bi-specific to specifically target myeloid or other immune suppressive populations could be investigated." (PMID 37771579, 2023). "p16Ink4a and p21Waf1/Cip1 could suppress tumor progression by inducing cellular senescence, the deletion of p16Ink4 and p21Waf1/Cip1 reduces CX3CR1 expression and inhibits monocytic-MDSCs (Mo-MDSCs) accumulation in tumors expressing CX3CR1, hence suppresses the tumor proliferation in mice model." (PMID 36945046, 2023). "To further understand the molecular mechanism by which the FGL2-blocking scFv induces CD69+CD8+ TM cell generation, we analyzed CyTOF data for chemokine receptors (i.e., CCR2, CXCR3, CXCR2, and CX3CR1) that may affect T cell infiltration and recruitment to tumor sites." (PMID 36759517, 2023). "Thus, the CX3CR1 antibody reduces the abundance of MDSC in the tumor." (PMID 37771579, 2023). "Thus, our model permits the direct comparison of Food and Drug Administration–approved anti–PD-1/L1 mAbs and further correlates successful tumor rejection with the level of CX3CR1+PD-1+CD8 + T cells, making this model a critical tool for optimizing and better utilizing anti–PD-1/L1 therapeutics." (PMID 36656137, 2023). "To test our hypothesis, we chose the CT26 tumor model as CT26 expresses CX3CR1 and PD-L1." (PMID 37771579, 2023).